AR (androgen receptor)
Diseases named in the same sentence as AR in open-access papers (continued):
Sharing a sentence is not in itself a finding about the gene and the disease.
tumor (continued). "Moreover, some studies noted that AR is implicated in tumor growth, so it could be a good target for molecularly targeted ESCC therapies." (PMID 36142861, 2022). "In that regard, increased tumour glycolysis is associated with castration-resistant metastatic PCa (mCRPC) and poor prognosis, and a rise in glucose consumption marks out neuroendocrine differentiation and metastasis, a known molecular adaptation to androgen-deprivation and AR-targeting therapies." (PMID 35039635, 2022). "In addition, the transition of tumor cells from AR-dependent to AR-independent signaling pathways may cause further resistance to ARSI." (PMID 35008817, 2021). "Combined with the lack of systematic differences before and after therapy, our observations suggest that assessments of single AR variants may be insufficient for a causal understanding of a tumor’s sensitivity to androgen-targeting therapies even if their detection can serve as a proxy of total AR." (PMID 33664492, 2021). "Here we found that, in addition to AR protein encoded by the AR locus, the AR transcription could also result in generating additional molecules, like circRNAs, to play roles via sponging the miRNAs to regulate cell invasion and likely tumor metastasis." (PMID 34127806, 2021). "Since lower tumor grades are associated with cells that are slower-growing and look well-differentiated, such as the normal breast tissue, it is logical to assume that high AR gene expression levels may also be indicative of less aggressive BCs." (PMID 34571711, 2021). "However, other studies indicated that Doc might interrupt microtubule-dependent trafficking of androgen receptor (AR) into the nuclei, and clinical data also linked cytoplasmic AR in circulating tumor cells with patients’ responses to Doc-chemotherapy." (PMID 32920545, 2020). "Tumor cell growth is sustained in castrate resistant PCa by a diversity of mechanisms including intratumoral or adrenal production of androgens, overexpression of AR or mutated AR forms, ligand-independent activation of AR or stabilization of hyper-responsive AR by chaperones." (PMID 32344908, 2020). "Interestingly, loss of AR expression in tumor stroma increases the risk of relapse after radical prostatectomy and it is commonly accepted that stromal AR expression progressively decreases during PCa progression, further enabling the growth of carcinoma cells." (PMID 31616657, 2019). "YWHAZ has been shown to directly associate with AR, to promote proliferation, migration, survival and resistance to apoptosis in PC cells, to increase in PC patient tumours as compared to benign tissue, and to positively correlate with presence of metastases in clinical tumour samples." (PMID 31043708, 2019). "Thus, the upregulation of PKD1 as a result of inhibition or loss of AR may promote tumor cell survival and contribute to therapeutic resistance to AR-targeted agents." (PMID 28077787, 2017). "However, the mechanisms leading to this differential expression of genes are currently unknown and need to be elucidated in order to have a better understanding towards the role of AR variants in tumor progression." (PMID 29069764, 2017). "Moreover, during these last years, several data suggested that AR variants could also promote tumor progression." (PMID 29069764, 2017). "Furthermore, higher AR expression (score 8~10) is inversely associated with smaller tumor size." (PMID 27340775, 2016). "In addition, we evaluated whether any clinical or tumor pathologic features predicted for AR+, PD-L1+, or BRCA1-associated TNBC." (PMID 28721372, 2016). "However, the high AR staining scores was associate smaller tumor size." (PMID 27340775, 2016). "Notably, three discrete AR-GSRs in rapid autopsy subject C-6 were present at high variant allele frequency, concentrated in the region of the AR gene encoding the AR ligand-binding domain, and clonal between tumours C-6A and C-6B." (PMID 27897170, 2016).
tumor (continued). "Approximately 90% of ERα-positive patients are also AR-positive (AR+), and this is associated with favorable prognosis i.e., longer relapse-free survival, response to therapy, older age at diagnosis, lower tumor grade, lower Ki67 positivity and smaller tumor size." (PMID 27548161, 2016). "This suggested that our disrupted network represents two broad adaptive mechanisms that may be at play in both our model and the human tumour data: alteration of transcriptional regulation in response to loss of AR regulation; and altered signalling driving proliferation and inhibiting cell death." (PMID 26553226, 2015). "Thus, it is the loss of AR signaling in the normal mammary gland under the influence of normal hormone levels and female steroid receptor status that increases the susceptibility of the mammary gland to further tumor-initiating insults." (PMID 23593223, 2013). "In addition, androgen receptor (AR) downregulation may denote a hormonal effect or cause in this tumor." (PMID 23354516, 2013). "Furthermore, studies on tumor samples from CRPC patients have revealed several mechanisms used by tumor cells to reactivate AR signaling, e.g. AR amplification or mutation, changes in the expression of enzymes involved in steroidogenesis, and intracrine androgen production." (PMID 23667504, 2013). "Somatic mutation of the AR is known to drive recurrent tumor formation in a significant percentage of patients undergoing hormone therapy, and it has been shown previously that selected AR mutants become receptive to activation by the environmental contaminant BPA." (PMID 18007998, 2007). "Recent data indicate that inhibition of KDM4B reduces global levels of both H3K9me3 and H3K27me3, resensitizing CRPC cells to the AR pathway inhibitor enzalutamide and inhibiting tumor growth." (PMID 41601922, 2026). "In light of prior work, our findings point to a FOXM1-associated 15-gene signature enriched in AR-low TNBC and associated with the high-proliferation and high-CIN phenotypes of this clinically challenging tumor type." (PMID 41751958, 2026). "Immunohistochemically, tumor cells were androgen receptor and Forkhead box protein A1-positive and estrogen- and progesterone receptor-negative, with a Ki-67 index of approximately 30%." (PMID 41913897, 2026). "AR signaling also relies on a network of coactivators that amplify its transcriptional activity and drive tumor progression, particularly after ADT." (PMID 41601922, 2026). "Among 96 metastatic NPC tumor samples, AR expression was observed in 35 cases (36.5%), predominantly in males (33/83, 39.8%)." (PMID 41633021, 2026). "Despite these sex differences, both tumor types retained an inverse relationship between AR signaling and immune infiltration." (PMID 41486951, 2026). "Among these, Q199, XDD60, and A79 exhibited comparable or even superior tumor growth inhibition efficacy compared with enzalutamide, a clinically prevalent AR antagonist." (PMID 41492471, 2026). "Inhibiting DOT1L impairs PC tumor growth and colony formation by suppressing AR and MYC signaling in preclinical models." (PMID 41601922, 2026). "In BRAFi resistant tumours and cell lines, we confirm AR upregulation predominantly in the MITFlow/AXLhigh undifferentiated/neural-crest like state, but it also occurs in the MITFhigh/AXLlow differentiated melanocytic state." (PMID 41872166, 2026). "As a transcription factor co-activator, ATAD2 partners with various factors, including the androgen receptor, E2Fs, and c-Myc, to facilitate tumor progression." (PMID 41158756, 2026). "We also examine how transcriptional and oncogenic regulators, including SOX2, MYC, and androgen receptor signalling, reprogramme sialyltransferase expression to produce tumour-specific sialoglycan profiles." (PMID 42132142, 2026). "In the female-specific panel, genes related to aberrant androgen signaling across tumor types like androgen receptor, PLXNA1, USP54, and PMEPA1 were influential." (PMID 42137503, 2026).
tumor (continued). "NSD2 and its H3K36 methyltransferase activity recruit AR to tumor-specific enhancers, where it cooperates with pioneer factors such as FOXA1, HOXB13, and ETS, redistributing AR binding and amplifying oncogenic signaling." (PMID 41601922, 2026). "This transformation reflects tumor aggressiveness and the development of resistance to androgen receptor–targeted therapies." (PMID 41438659, 2026). "Functionally, GNL3 knockdown sensitizes CRPC cells to AR antagonists and impairs tumor growth and metastasis." (PMID 41772945, 2026). "This study aimed to evaluate AR expression at both mRNA and protein levels in GBM tissue and to explore its potential association with magnetic resonance imaging (MRI)-defined tumor volume." (PMID 41874742, 2026). "Perhaps unsurprising is that our analysis showed that PRAD has the highest levels of AR activity compared with other tumors, reflecting the tumor dependence on androgens." (PMID 41486951, 2026). "Once again, AR activity exhibited significant negative correlations with these immune signature activities in GTEx samples, suggesting conserved AR regulation of immunity in healthy tissue and tumor." (PMID 41486951, 2026). "Cellular stemness and EMT are key features of lineage plasticity in PCa, which enable tumor cells to adapt to AR pathway inhibition." (PMID 41510165, 2026). "Nanocarriers provide tumor‐specific concentration of anti‐androgens, AR degraders, or AR‐axis siRNAs and allow triplet combinations (e.g., ADT + TNP loaded with taxane + immunomodulator)." (PMID 41521160, 2026). "This complex amplifies the expression of androgen-responsive genes such as PSA, thereby potentially enhancing AR-driven tumor growth—a mechanism particularly relevant in CRPC." (PMID 41602838, 2026). "AR mRNA expression showed a strong trend toward positive correlation with Ki67 proliferation index (r = 0.44, p = 0.07) and tumor volume (r = 0.36, p = 0.06 for T1-enhancing regions; r = 0.40, p = 0.03 for non-enhancing FLAIR-hyperintense regions)." (PMID 41874742, 2026). "SCL tumors have reduced AR activity and increased stem-cell activity that promotes tumor formation, which contributes to poor clinical outcomes." (PMID 41954995, 2026). "Leveraging a unique dataset with matched biopsies before and after AR inhibition with enza treatment, we identified enriched immune cell signaling pathways and IFNγ signaling activity in the patients’ on-treatment tumor samples that showed AR deactivation." (PMID 41486951, 2026). "The loss of AR signaling, low prostate-specific antigen (PSA) levels, visceral metastases, and significantly reduced survival are the main characteristics of this tumor subtype." (PMID 41689691, 2026). "Androgen deprivation therapy heightens tumor sensitivity to PARP treatment, and PARP enzymatic activity is associated with AR function." (PMID 41550797, 2026). "Leveraging a network computational approach, we comprehensively investigated the relationship between AR activity and tumor-infiltrating leukocytes across various cancer types and within sexes." (PMID 41486951, 2026). "In many cases, tumor cells still depend on persistent or restored AR signaling under castrate conditions." (PMID 42255210, 2026). "In this study, we investigated how AR activity correlates with tumor-infiltrating leukocytes, patient prognosis, and immunotherapy response across cancers and sexes." (PMID 41486951, 2026). "Significant negative correlations were observed between each signature score and AR activity across all TCGA tumor samples (n = 10,340), with Pearson correlation values ranging from −0.39 to −0.44." (PMID 41486951, 2026). "In this study, we applied a network computational approach to investigate AR, ER, and PR activity in human cancers using 33 bulk tumor RNA-seq datasets from TCGA cohorts." (PMID 41486951, 2026). "Other tumor characteristics such as a lower grade, lower mitotic score, less frequent metastasis, and tumor recurrence, correlated well with AR positivity." (PMID 40150035, 2025).
tumor (continued). "Since the clinical demonstration of tumor regression following androgen blockade, inhibition of the androgen/AR axis has remained the cornerstone of PCa treatment." (PMID 40570057, 2025). "CD38, linked to growth arrest through apoptotic pathways, and AURKA are targeted by alisertib to inhibit AR-mediated tumor growth." (PMID 40656519, 2025). "AR not only influences the growth of tumor cells themselves but also affects tumor development and progression by regulating immune cell responses in the tumor microenvironment." (PMID 40008000, 2025). "Mechanistically, EGCG modulates AR-regulated microRNAs, downregulating oncogenic miRNA-21 while upregulating tumor-suppressive miRNA-330, which modulates the AKT/P-AKT/caspase-3/MMP-2/MMP-9 signaling axis." (PMID 41020902, 2025). "Simultaneous targeting of the PI3K/AKT and AR pathways with the combination of copanlisib and darultamide was found to decrease the tumor burden of SCID mice with LuCaP 35 PDX tumors." (PMID 40427108, 2025). "Overexpression of MED12 is highly prevalent in castration-resistant prostate cancer (CRPC) and promotes tumor progression by enhancing AR activity." (PMID 40940746, 2025). "Mechanistically, androgen receptor (AR) signaling suppresses the activity and stemness of tumor-infiltrating CD8+ T cells in males by modulating epigenetic and transcriptional differentiation programs." (PMID 40547923, 2025). "In conclusion, our study offers profound insights into the diverse biological functions of STARD4 in PCa, including its roles in inhibiting tumour growth, regulating lipid metabolism, and modulating the AR signalling pathway." (PMID 41331871, 2025). "When cancer cells detach from the primary tumor and lose adhesion to the extracellular matrix, stem-like cells can acquire AR, increasing their survival and metastatic potential." (PMID 40024947, 2025). "For example, oncogenic TFs such as MYC, AR, and ER are known to be constitutively active in a wide range of cancers and contribute to tumor progression and therapy resistance." (PMID 40507351, 2025). "In mice, castration retards the growth of androgen receptor (AR) positive human RCC tumor xenografts." (PMID 41034844, 2025). "Another example is CCS1477, a newer small-molecule inhibitor that also blocks the p300/CBP bromodomain and has demonstrated the ability to reduce tumor growth in AR-driven and mCRPC models." (PMID 41235005, 2025). "Immunohistochemical analysis showed absent estrogen receptor (ER) and progesterone receptor (PR) expression, weak-to-moderate androgen receptor (AR) positivity in 40 % of tumor cells, strong HER2 staining (3+), and a Ki-67 proliferation index of 25 %." (PMID 41562063, 2025). "For instance, GPCR signaling can activate the Hippo-YAP/TAZ pathway, which cooperates with AR and other transcription factors to drive aggressive tumor phenotypes." (PMID 41347146, 2025). "Meanwhile, NGS of ctDNA can detect actionable mutations (e.g., those in BRCA2, AR, and PIK3CA) and track tumor burden over time." (PMID 40427518, 2025). "The androgen receptor (AR) transduces the effects of circulating and tumor-derived androgens to the nucleus through ligand-induced changes in protein conformation, localization, and chromatin engagement." (PMID 40681873, 2025). "These mutations can cause the emergence of AR-null phenotypes that lack PSMA expression, making the tumor cells less susceptible to targeting by the radioligand and leading to poorer outcomes in mCRPC patients." (PMID 39796175, 2025). "Androgen Deprivation Therapy (ADT), the standard initial treatment for hormone-sensitive prostate cancer, induces tumor regression by suppressing AR activity." (PMID 40643528, 2025). "Several AR-targeting degraders are currently under investigation, with early candidates demonstrating potent anti-tumor activity and favorable pharmacokinetic profiles." (PMID 41228300, 2025).
tumor (continued). "Previously it has been demonstrated that aberrant translation in PCa tumoral cells is required to maintain AR-low PCa cells promoting tumor heterogeneity." (PMID 40832297, 2025). "Androgen’s activity is regulated through the androgen receptor (AR), which is a crucial player in tumor initiation and therapy resistance, and it is expressed in the prostatic epithelium and prostatic stroma cells." (PMID 41514571, 2025). "In turn, the RSGs influence AR function and affect both ligand-bound and ligand-independent AR transcriptional activity, thereby enabling tumor progression." (PMID 41301045, 2025). "ATF3 directly inhibits AR transcriptional activity and downstream targets (e.g., PSA), while NR2F1 loss promotes tumor heterogeneity and enzalutamide resistance." (PMID 40470696, 2025). "Various AR gene mutations are closely associated with resistance to CRPC and affect tumor cell growth and treatment response through different mechanisms." (PMID 40008000, 2025). "In animal models, it was shown that the role of AR depends on its location (tumor promoter in stroma and tumor suppressor in the epithelium)." (PMID 40336533, 2025). "The major circulating androgen, testosterone, and its derivative 5α-dihydrotestosterone (DHT) bind to AR, forming AR-androgen complexes that can bind to androgen-responsive elements of the tumor DNA, and influence tumor growth in hormone-sensitive PCa." (PMID 41226028, 2025). "Early in vivo tumor regrowth assays have demonstrated the importance of AR signaling; however, they lack the robust molecular stratification required to capture heterogeneity among different patient subgroups." (PMID 40427518, 2025). "This framework underscores how GPCRs serve as central nodes integrating signals from the tumor microenvironment, AR pathway, and intrinsic oncogenic drivers." (PMID 41347146, 2025). "Their role, however, is context-dependent—e.g., RhoB is tumor-suppressive in AR-null PCa but oncogenic in AR-positive tumors." (PMID 41301045, 2025). "Preclinical studies have demonstrated that inhibition of the AR can upregulate the expression of MHC class II molecules and tumor-associated antigens, thereby enhancing immune recognition of tumor cells and potentiating antitumor immune responses." (PMID 40936705, 2025). "Considering each tumor histotype, in OS, 5 out of 6 (80%) male patients presented sequence alterations (deletion and duplications) on the AR gene." (PMID 41514647, 2025). "While the oncogenic functions of AR signaling have been well documented, numerous evidence indicates AR can also exhibit tumor-suppressive roles in certain cancer contexts." (PMID 39744510, 2025). "Being in line with tumor suppressive activity induced by SAL, some tumor suppressors are known to be within the AR signaling and SAL-induced cellular senescence." (PMID 41264145, 2025). "The mean AR staining score in tumor epithelial cells was 8, but with large variability observed (median 8, Q1 4, Q4 12, range 0–12, n = 156)." (PMID 40841830, 2025). "Based on the dynamic changes in the androgen receptor (AR) gene and AR-V7 in circulating tumor cells, researchers have established a method to predict sensitivity to chemotherapy and endocrine therapy in metastatic castration-resistant prostate cancer (mCRPC)." (PMID 41247642, 2025). "For example, the MAP3K2 protein, a key upstream kinase in the MAPK signaling pathway, can activate downstream MAP2Ks, participate in the cellular stress response and immune response, participate in tumor cell proliferation and regulate AR protein degradation." (PMID 40078537, 2025). "While TANs have been linked to more aggressive tumor behavior, their impact on disease progression and their interactions with other tumor markers like AR are not fully understood." (PMID 40734715, 2025). "Decreased JARID1D expression in tumor cells correlated with reduced AR activity, increased MAOA levels, and elevated RANKL secretion." (PMID 39816691, 2025).